IL6 (interleukin 6)
Diseases named in the same sentence as IL6 in open-access papers (continued):
Sharing a sentence is not in itself a finding about the gene and the disease.
Insulin resistance (continued). "Various proinflammatory cytokines such as tumor necrosis factor-α (TNF-α), interleukin-6 (IL-6), and interleukin-1β (IL-1β) often participate in the pathogenesis of MS and insulin resistance." (PMID 26728949, 2016). "With the associations between inflammatory cytokines (e.g., IL-6, TNF-α, and hs-CRP) and insulin resistance, prediabetes or T2DM had been widely researched." (PMID 27478850, 2016). "Critically ill patients demonstrate elevated levels of TNF and IL-6 and these patients and T2D share phenotypical similarities such as hyperglycemia, insulin resistance, and systemic inflammation." (PMID 27148273, 2016). "A number of these adipokines, such as adiponectin, leptin, TNF-α, resistin, PAI-1, IL-6 and MCP-1, were found to be directly related to insulin resistance and associated morbidities." (PMID 27651836, 2016). "Conversely, in Italian Caucasian females, increased plasma levels of IL-6 were found in obese individuals carrying GG genotype suggesting that fat mass is a major determinant of an increase in IL-6 production and insulin resistance." (PMID 25897330, 2015). "Various inflammatory cytokines, including IL-6 and TNF-α, have been shown to activate NF-κB to cause insulin resistance." (PMID 26843885, 2015). "In these Ikk2ca transgenic mice, hepatocytes is the primary source of IL-6 production, which plays a key role in insulin resistance." (PMID 26219821, 2015). "Proinflammatory cytokines, such as IL-6 and TNF-α, are adipokines that have been associated with the development of insulin resistance and type 2 diabetes." (PMID 26170870, 2015). "Our previous study indicated that miR-200s contribute to hepatic insulin resistance induced by IL-6 via targeting FOG25." (PMID 26111969, 2015). "We also found that Oligonol suppressed the expression of inflammatory cytokines such as IL-6, thus exhibiting anti-inflammatory effects, and regulated insulin resistance through the STAT3–SOCS3 and AMPK pathways." (PMID 26077338, 2015). "Similar to TNF-alpha, IL-6 is a proinflammatory adipokine that correlates with body weight and insulin resistance." (PMID 26640706, 2015). "Inflammatory cytokines (e.g., TNFα, MCP-1, IL-6) worsen insulin resistance and inflammatory signaling in mice." (PMID 25816097, 2015). "hsCRP is produced by the liver, primarily by the action of interleukin-6, a cytokine that increases in the conditions of visceral obesity and insulin resistance." (PMID 26089902, 2015). "M1 macrophages secrete various pro-inflammatory cytokines, such as TNF-α and IL-6, which induce insulin resistance via the IKKβ- and JNK-mediated inhibitory serine phosphorylation of insulin receptor substrate (IRS) proteins." (PMID 26197341, 2015). "Whereas increased interleukin-6 (IL-6) secretion from adipose tissue positively correlates with insulin-resistance in obese subjects." (PMID 26140541, 2015). "Reports IL-6 and TNF-α are the major inflammatory adipokines that impair insulin signaling and its actions that result in the associated development of insulin resistance and type 2 diabetes." (PMID 26170870, 2015). "TNF-α and IL-6 are produced by adipose tissue monocytes and macrophages and lead to insulin resistance." (PMID 26110385, 2015). "Elevated plasma IL-6 levels play an important role in insulin resistance by impairing insulin signaling." (PMID 26111969, 2015). "The presence of peripheral insulin resistance in other catabolic states has been associated with the overproduction of the proinflammatory cytokines, tumor necrosis factor (TNF)-α or interleukin (IL)-6." (PMID 26426068, 2015). "Adipocyte-derived IL-6 was shown to regulate hepatic insulin resistance via upregulation of suppressor of cytokine signaling 3 (SOCS3) which in turn induces an increase in SREBP-1c and DNL." (PMID 26090470, 2015).
Insulin resistance (continued). "Yet, A-769662 was also shown to have beneficial effects on both hepatic steatosis and insulin resistance, thus emphasizing the potential therapeutic implications for AMPK activation in anti-IL-6 responsive RA patients and associated metabolic syndrome." (PMID 26474486, 2015). "The two groups were well matched for BMI and circulating levels of biomarkers involved in glycaemic control, indices of insulin resistance, inflammation (IL-6, CRP, TNF-α, MIF), oxidative stress and SpO2." (PMID 24733551, 2014). "The collective findings suggest that endogenous IL‐6 is important for the prevention of insulin resistance induced by HFD." (PMID 24997069, 2014). "In MS patients, several reports have demonstrated increased IL-6 levels related to BMI and insulin resistance." (PMID 25548896, 2014). "Both hsCRP and IL-6 are well-characterized inflammatory markers in type 2 diabetes, being independently related to insulin resistance and to the progression of atherosclerosis." (PMID 25258627, 2014). "Inflammatory cytokines, such as TNF-α, IL-6 and others, have been shown to promote insulin resistance and liver inflammation." (PMID 24489777, 2014). "Most women with polycystic ovary syndrome (PCOS) have insulin resistance, hyperinsulinemia, and elevated serum IL-6 levels." (PMID 25096410, 2014). "The monocytes, macrophages, lymphocytes coupled with the cytokines secreted by these cells – in particular, TNF-α and IL-6 – contribute to insulin resistance and atherosclerotic plaques." (PMID 25364704, 2014). "Increased levels of acute phase proteins such as C-reactive protein (CRP), interleukin 6 (IL6) and sialic acid have been shown in patients with T2DM and insulin resistance and are known to be associated with CVD." (PMID 24955136, 2014). "Activin A has also been proposed to have a pro-inflammatory effect, stimulating the secretion of TNF alpha and IL6 cytokines, both well-known important players in the pathogenesis of insulin resistance." (PMID 24763182, 2014). "Many of them, including monocyte chemotactic protein (MCP)-1, tumor necrosis factor (TNF)-α, interlukin (IL)-1, IL-6 and IL-8, have been reported to promote insulin resistance." (PMID 24733068, 2014). "The purpose of this study was to determine both the role of IL‐6 on HFD induced glucose intolerance, and in response to voluntary physical activity in the prevention of insulin resistance in IL‐6‐deficient mice." (PMID 24997069, 2014). "Increased VAT acts as a metabolically active tissue that produces numerous inflammatory cytokines such as hs-CRP, tumor necrosis factor alpha (TNF-α), and interleukin-6 (IL-6) and promotes both hepatic and systemic insulin resistance." (PMID 25111123, 2014). "In its entirety, the findings of this study suggest that endogenous IL‐6 is important for the prevention of insulin resistance induced by HFD." (PMID 24997069, 2014). "SCO also blunted the TNFα-mediated increase in IL-6, which is another pro-inflammatory cytokine that has been shown to induce insulin resistance in adipocytes." (PMID 24915004, 2014). "The adipocytokines TNFα and IL-6 derived from adipose tissues are strongly suggested to promote insulin resistance and inflammation in the liver." (PMID 24858832, 2014). "Consistent with our metabolic data showing insulin resistance, the levels of IL-6 in the liver and adipose tissue were higher in CD1d−/− mice than WT mice." (PMID 24465369, 2014). "The anti-inflammatory properties of IL-6 are illustrated by IL-6−/− mice, which exhibit hepatosteatosis, insulin resistance, and liver inflammation." (PMID 25339958, 2014). "The increased visceral adiposity induces a decrease in adiponectin, which has an anti-inflammatory action, and an increase in inflammatory cytokines, such as tumor necrosis factor-α, interleukin-6, and free fatty acids, which raise insulin resistance." (PMID 25024746, 2014). "TNF-α and IL-6, two well-known pro-inflammatory cytokines, affect insulin action and promote insulin resistance." (PMID 24913911, 2014).
Insulin resistance (continued). "IL-6 is suggested to play a role in insulin resistance, as its circulating levels are positively related to adiposity and IL-6 is overexpressed in fat cells from insulin-resistant subjects." (PMID 24918199, 2014). "Considering the relationship between IL-6 levels and insulin resistance, metformin has the potential to affect serum IL-6 levels in PCOS patients." (PMID 25096410, 2014). "Once over-activated by TNF-α and IL-6, Th22 cells exacerbate insulin resistance and aggravate β-cell injuries, thus promoting disease progression." (PMID 24465695, 2014). "The condition is exacerbated owing to the combination of insulin resistance as well as greater expression of placental inflammation by the cytokines, namely, IL-6." (PMID 25258478, 2014). "This impaired glucose tolerance in KO RUN is an indicator of developing insulin resistance, and these findings suggest that IL‐6 has an important role in the beneficial effects of physical activity on HFD‐induced glucose intolerance." (PMID 24997069, 2014). "Other studies have also revealed that proinflammatory cytokines IL-6 and TNF were among the first to be implicated as a predictor or pathogenic mediator of insulin resistance, CVD, and in patients with type 2 diabetes." (PMID 25309773, 2014). "Inflammatory cytokines, including TNF-α, IL-6, and IL-8, have been involved in the pathogenesis of insulin resistance." (PMID 25202741, 2014). "Nevertheless, plasma levels of IL-6 have been reported to be increased in obese patients and IL-6 overexpressed in adipocytes from subjects with insulin resistance." (PMID 25514415, 2014). "This study demonstrated a significantly positive influence of an anti-IL-6 antibody on the progression of insulin resistance." (PMID 24897026, 2014). "The collective findings suggest that endogenous IL‐6 is important for the prevention of insulin resistance leading to type 2 diabetes." (PMID 24997069, 2014). "PM2.5 exposure led to hyperglycemia and insulin resistance, which was accompanied by increased hypothalamic IL-6, TNFα, and IKKβ mRNA expression and microglial/astrocyte reactivity." (PMID 25358444, 2014). "In particular, IL-6 seems to induce insulin resistance impairing hepatic signalling and affecting the phosphorylation of insulin receptor substrate 1 (IRS-1), glucose transporter 4 (GLUT–4), and other specific transcription factors." (PMID 25548896, 2014). "Hyperglycemia results in increased IL-6 levels, and treatment with IL-6 induces hyperglycemia and insulin resistance in humans." (PMID 24733068, 2014). "IL-6 administered peripherally results in elevated levels of triglycerides and glucose, whilst concurrently increasing the degree of insulin resistance." (PMID 25309775, 2014). "In particular, high-sensitivity C-reactive protein (hsCRP) and interleukin-6 (IL-6) have been clearly involved in both insulin resistance and atherosclerosis prediction." (PMID 25258627, 2014). "This has been shown through in vivo murine studies to involve NF-κB activation and is once again characterised by the production of cytokines, such as IL-6, IL-1, and TNFα, resulting in both hepatic and systemic insulin resistance." (PMID 24830559, 2014). "Among these molecules, the members of the interleukin-6 (IL-6) family (thus, potentially CT-1) have been directly correlated with development of insulin resistance in asymptomatic subjects as well as in frankly diabetic patients." (PMID 23690661, 2013). "In vitro experiments revealed that IL-6 induced insulin resistance in hepatocytes, adipocytes, and in skeletal muscle cells after treatment with high doses." (PMID 23861558, 2013). "We used ELISA to examine pro-inflammatory cytokines IL-1, IL-6 and TNFα in the plasma, which are primarily involved in insulin resistance and T2D." (PMID 23837842, 2013).
Insulin resistance (continued). "Recently, our group demonstrated a positive correlation between plasma endotoxin concentration and both proinflammatory cytokines (especially IL-6) and insulin resistance in obese adolescents." (PMID 23509418, 2013). "All of these observations show a central role of pre-adipocytes and adipocytes in the inflammatory status and LGI of adipose tissue mainly mediated by IL-6 secretion and its implication in insulin resistance." (PMID 24073286, 2013). "Adiponectin is known to play a protective role in the development of insulin resistance and diabetes, both of which are positively associated with elevated levels of CRP and IL-6." (PMID 23984329, 2013). "A 1-month reduction of the postoperative acute phase response led to a decrease in IL-6 and insulin resistance." (PMID 22829443, 2013). "Inflammatory markers (TNF-α, IL-1, IL-6) are associated with a reduction of AS160 activities, resulting in increased insulin resistance." (PMID 24098343, 2013). "It has been shown that IL-6 upregulation in adipocytes leads to insulin resistance by activating SOCS3 in target cells like hepatocytes." (PMID 24073286, 2013). "Increased peripheral insulin resistance has been coupled with elevated expression of bioactive inflammatory mediators including adipokines (IL-6 and TNF-alpha) which lead to insulin resistance." (PMID 23671867, 2013). "Circulating IL-6 elicits many types of responses, and has been found to correlate with insulin resistance and altered carbon metabolism." (PMID 23527073, 2013). "Primary cytokines involved in insulin resistance-associated inflammation are tumor necrosis factor alpha (TNF-α) and interleukin-6 (IL-6)." (PMID 24101915, 2013). "It is up-regulated by insulin resistance-inducing cytokines as IL-6 in adipocytes, representing a molecular connection between insulin resistance and obesity." (PMID 23482058, 2013). "For instance, GHR knockout mice have reduced levels of pro-inflammatory cytokines implicated in development of insulin resistance (TNF-α and IL-6), possibly as a consequence of anti-inflammatory effects of increased levels of adiponectin in these mutants." (PMID 23483710, 2013). "Our findings suggest that increased insulin resistance (HOMA-IR), oxidative stress (ADMA, HDL), and inflammation (IL-6) due to AO are independently associated with PAD in HD patients, which are not analyzed in previous studies." (PMID 23840739, 2013). "In that study, insulin resistance induced by progranulin was significantly improved by a neutralizing antibody against IL-6, implicating IL-6 as a mediator of progranulin-induced insulin resistance in adipocytes." (PMID 23409033, 2013). "Chronic inflammation of visceral adipose tissue (VAT) is a major contributor to insulin resistance mediated by adipose tissue-released adipokines (for example, IL-6, TNFα, MCP-1 and resistin)." (PMID 23837842, 2013). "On the other hand, a number of in vitro and in vivo studies demonstrate that IL-6 is capable of inducing insulin resistance." (PMID 24455420, 2013). "Yet, sleep deprivation over time leads to elevation of somnolence-inducing proinflammatory cytokines, such as Interleukin-6, which however exert untoward metabolic effects, including insulin resistance." (PMID 23637777, 2013). "A chronic inflammatory state leads to the production of truncal fat adipokines (e.g., TNF-α, IL-6, and IL-8) which increase insulin resistance and endothelial dysfunction." (PMID 23843781, 2013). "During high fat diet consumption, ATM production of TNFα and IL-6 is closely related to the onset of insulin resistance and glucose intolerance." (PMID 23469154, 2013). "Incubation of the rat L6 myotubes with 200 ng/mL recombinant IL-6 induced insulin resistance on the level of diminished Akt phosphorylation after 96 h and in primary human myotubes after 48 h." (PMID 23861558, 2013).
Insulin resistance (continued). "In primary human adipocytes, it prevents insulin resistance and down-regulates inflammation, by attenuating IL-6, IL-1β, IL-8 and MCP-1 expression." (PMID 23698776, 2013). "Chronic low-grade inflammation and pro-inflammatory cytokines, such as TNF-α and IL-6 as well as others, contribute to the development of glucose intolerance and insulin resistance-related metabolic syndrome and T2D." (PMID 23326455, 2013). "We will rather focus on the prototypical adipokines (TNF-α, IL-6, leptin, adiponectin, and resistin) highlighting their roles in the development of insulin resistance as well as in immunity and inflammation." (PMID 24455420, 2013). "IL-6-mediated insulin resistance involves activation of proinflammatory kinases that converge at the IRS-1 level." (PMID 23533500, 2013). "Other cytokines, such as tumor necrosis factor (TNF)-α and interleukine (IL)-6, have also been related to insulin resistance." (PMID 23482058, 2013). "After surgery, worsening of insulin resistance was correlated with increased systemic as well as adipose tissue content of IL-6." (PMID 24023413, 2013). "Vitamin D attenuates the expression of proinflammatory cytokines involved in insulin resistance such as interleukins, IL-1, IL-6, TNF-a, also down regulates NF-Kb (Nuclear factor) activity." (PMID 23443033, 2013). "In adipose tissue and liver, however, IL-6 will exert proinflammatory activities, increasing insulin resistance by upregulating SOCS3 (suppressor of cytokine signaling 3) which, in turn, impairs insulin-induced insulin receptor and IRS1 phosphorylation." (PMID 24455420, 2013). "Recent data point to the fact that central resistin induces hepatic insulin resistance by increasing the expression of proinflammatory cytokines, such as IL-6 and TNFα, via an unidentified mechanism mediated by the autonomic nervous system." (PMID 23710116, 2013). "Further adding to this controversy, mice with the genetic deletion of IL-6 have significant hepatic inflammation and develop insulin resistance." (PMID 23028874, 2012). "Abdominal subcutaneous tissue produces a variety of adipokines, such as TNF-α and IL-6, which has an important role in inflammation and insulin resistance via endocrine, paracrine, or autocrine signals." (PMID 21822486, 2012). "The present study found a positive correlation between endotoxin and both pro-inflammatory cytokines (especially, IL-6) and insulin resistance." (PMID 22989045, 2012). "Adipose tissue secretes various cytokines including TNF-α, IL-6 and adipokines such as leptin and adiponectin involved in glucose metabolism and insulin resistance." (PMID 22816003, 2012). "Among the inflammatory markers, IL-6 has emerged as one of the potential mediators between obesity and insulin resistance/diabetes." (PMID 22272193, 2012). "We have shown that IL-6 activates AMPK, a mediator of mitochondrial biogenesis, in adipose tissue; however, IL-6−/− mice fed a high fat diet have been reported to develop insulin resistance." (PMID 23240005, 2012). "Activation of NF- κB is involved in the initiation of downstream production of cytokine (interleukin-6 [IL-6]) that leads to insulin resistance." (PMID 22451839, 2012). "GTCs supplementation was also found to decrease plasma levels of insulin, TNF-α, and IL-6 in a rat insulin resistance model." (PMID 22312273, 2012). "Up-regulated in states of insulin resistance, IL-6 differentially regulates androgen receptor transactivation via three distinct signaling transduction pathways, the overall effect depending on the balance among these pathways and the androgen concentrations." (PMID 22713099, 2012). "HF-induced insulin resistance is due, in part, to increases in macrophage infiltration and the local levels of TNFα and IL-6 in skeletal muscle and the subsequent deleterious effects of these cytokines on insulin signaling in muscle tissue." (PMID 22272317, 2012).